CDKN2A (cyclin dependent kinase inhibitor 2A)
Diseases named in the same sentence as CDKN2A in open-access papers (continued):
Sharing a sentence is not in itself a finding about the gene and the disease.
cancer (continued). "Several known cancer-related genes, including EGFR and CDKN2A/2B, are harbored in these regions." (PMID 26386145, 2015). "Specifically, the automated procedure was not able to map some well-known cancer genes, including cyclin-dependent kinase inhibitor 2A (CDKN2A), F-box and WD repeat domain containing 7 (FBXW7), and E2F transcription factor 3 (E2F3), to a hallmark." (PMID 26369414, 2015). "One of the first studies identified PENK and CDKN2A methylation in the plasma of 21.4 and 45.4% of patients with localized pancreatic cancer, however, this study did not include a cancer-free control group." (PMID 25988180, 2015). "We chose CDKN2A and RASSF1 since hypermethylation of these genes has been widely reported in a variety of cancers including NSCLC, and the EN1 promoter region since hypermethylation of EN1 had been previously reported in a lung tumor cell line but not yet in primary NSCLC tumors." (PMID 22726460, 2012). "For example, frequent hypermethylation of CDKN2A, RASSF1, CDH13, and other genes has been observed in sputum samples from cancer-free smokers, suggesting that they may be hypermethylated early." (PMID 21577262, 2011). "We found that the expression ratio of CCND1 to CDKN2A clearly classified RB1-positive and -negative cancer lines, the predictive accuracy of which was superior to that of individual CDKN2A or CCND1, respectively." (PMID 21447152, 2011). "An inverse correlation of CDKN2A and RB1 expressions has been reported in several types of cancers." (PMID 21447152, 2011). "Furthermore, the canonical cancer gene RB1 and the CDKN2A/B locus are present in two of its co-lost regions." (PMID 20052266, 2010). "Furthermore, expression of ageing-related replicative senescence marker CDKN2A, as assessed by qRT-PCR, was significantly increased 1.8-fold in MSCs from MGUS and MM patients, compared with younger non-cancer controls (p = 0.02 and p = 0.006, respectively, Kruskal-Wallis test with Dunn’s post-test)." (PMID 40263435, 2025). "Therefore, we assume that CDKN2A/CDKN2B aberrations reflect a general mechanism of cancer rather than a specific prognostic group of children with T-ALL." (PMID 38783324, 2024). "In conclusion, CDKN2A ALT was associated to a worse OS in patients who were not treated with ICIs; the addition of ICIs also might improve clinical outcomes in pan-cancer patients." (PMID 38822443, 2024). "Notably, deletions of the CDKN2A and PTEN genes were observed in 3 patients (SN38, SN50, and SN54) with late stage cancer (IVb) and metastasis (T3NxM1), which may warrant further investigation." (PMID 39409874, 2024). "While the genetic alterations in CDKN2A have been reported in several single forms of human cancers, there is a lack of a comprehensive study that deeply describes the state and the type of the genetic and epigenetic modifications of CDKN2A in a panel of human tumors." (PMID 37626750, 2023). "The results showed the correlations between CDKN2A expression and different infiltration levels of CD4+ T cells, CAF, progenitors, NK T cells, Tregs, B cells, Endo, Eos, HSC, Tfh, γ/δT, neutrophils, monocytes, macrophages, dendritic cells, NK cells, Mast cells and CD8+ T cells in pan-cancer." (PMID 36961395, 2023).
cancer (continued). "Importantly, circMET regulated the expression of CDKN2A, a critical tumor suppressor gene, and SMAD3 which could maintain the stem cell properties of cancer stem-like cells." (PMID 35042525, 2022). "The expression of CDKN2A, CDKN2B, CDKN2C, and CDKN2D was positively correlated with the T stage, and the expression of CDKN2A, CDKN2B, and CDKN2C was positively correlated with the pathological stage, indicating that patients with more advanced cancer tended to express higher mRNA levels of INK4." (PMID 35771229, 2022). "However, the genes CDKN2A and GPX4 were highly expressed in cluster A. High expression of GPX4 may inhibit ferroptosis, which in turn promotes the proliferation of cancer cells, resulting in poor prognosis, which is consistent with our findings." (PMID 36132144, 2022). "In addition, a strong relationship between CDKN2A deletion and distant metastasis was observed in cancers without lymphatic metastasis, but not in cancers with lymphatic metastasis." (PMID 35004325, 2021). "MITF-E318K was observed not only in familial and multiple CM cases, in association or not to concurrent pathogenic variants of the Cyclin Dependent Kinase Inhibitor 2A gene (CDKN2A), but also in sporadic cases, and in some CM cases showing association to other cancer types." (PMID 34573422, 2021). "In addition to the potential for combinatorial targeting of CDKN2A and MAP3K1, two over-expressed druggable proteins residing within this central component of the network were found to interact with more than one CIS-derived candidate cancer protein." (PMID 34154646, 2021). "In addition, OS of pan-cancer patients (n=9384) without CDKN2A deletion was longer than those (n=1418) with CDKN2A deletion in TCGA project (p<0.001)." (PMID 35004325, 2021). "CDKN2A SCND leads to inactivation of both P16INK4a and P14ARF (two endogenous inhibitors for CDK4 and MDM2) in >90% CDKN2A-deleted cancers, it needs to study whether CDK4 and MDM2 inhibitor drugs could be used to prevent hematogenous metastasis of cancers." (PMID 35004325, 2021). "Indeed, FAT1, CASP8, CDKN2A, and NOTCH1 mutations were found more frequently in these tumors compared with other HNCs malignancies and other squamous non-HNCs cancers." (PMID 34440249, 2021). "CIMP-H, MCC and CDKN2A methylation was absent or rare in MSI-L carcinomas." (PMID 34298744, 2021). "Second, there were cases in TCGA tumors and CCLC cancer cell lines in which JAK2 was deleted in the absence of CDKN2A/CDKN2B or PTPRD deletion, suggesting that JAK2 deletion alone may have a functional benefit to cancer cells." (PMID 28977839, 2017).
cancer (continued). "Besides, other studies have identified genes with significantly different methylation between different subtypes, and the differentially methylated genes (including CDKN2A, APC, CDH13, THBS2 and ERG) have been utilized to distinguish these different histological subtypes of cancers." (PMID 26862903, 2016). "Besides VHL and SETD2, the compound was also selective for cancer cells with mutation in PTEN and CDKN2A (data not shown)." (PMID 25853938, 2015). "Human and zebrafish genomes are 70% similar based on conservation of individual genes, with several cancer-associated genes found in mammals but not in the zebrafish, including BRCA1, p16 (CDKN2A), BRCA1, LIF, OSM, IL6 and PML (G.D. and J.N.B., unpublished observation)." (PMID 24973744, 2014). "However, of the 19 patients with MSI-H/CDKN2A methylation positive cancers, 14 (74%) died of disease, in comparison to 20/42 (47.6%) of patients with MSI-H/CDKN2A methylation negative cancers." (PMID 22925370, 2012). "Furthermore, the extent of methylation was significantly greater in EAC compared to BE for six genes (CDKN2A, ID4, RBP1, RUNX3, SFRP1, and TMEFF2), suggesting that methylation of these genes occurs early in the progression of BE, with increased methylation as the disease advances toward cancer." (PMID 40149421, 2025). "Of note, with the frequency of CDKN2A ALT extracted from the MSK-MetTropism cohort, we found a significant correlation between CDKN2A ALT frequency and ORRs (r, 0.58; P = 0.002), suggesting that cancer patients with CDKN2A ALT might benefit more from immunotherapy." (PMID 38822443, 2024). "In summary, epigenetic regulation by DNA methylation (e.g., CDKN2A) could represent a key driver affecting the nerve–cancer crosstalk leading to PNI in HNSCC and serve as a promising drug target for therapeutic intervention in the cancer dissemination via nerve tracks." (PMID 37240283, 2023). "However, whether the inactivation of the CDKN2A gene by SCND affects hematogenous metastasis of human cancers has not been reported previously." (PMID 35004325, 2021). "Therefore, we cannot rule out the fact that the inactivation of CDKN2A in cancer cells may indirectly account for AT browning (at least partly via β3-adrenergic activation) participating in the development of cachexia." (PMID 32971832, 2020). "Indeed, as proof of the validity of our method, we identified many genes that are known to be differentially methylated across various cancer types (CDKN2A, CDKN2B, MGMT, SFRP1), in addition to many novel genes not previously known to be regulated by DNA methylation." (PMID 25486910, 2014). "Patients with rare cancers more frequently had CDKN2A and BRAF genetic alterations compared to patients with non-rare cancers, leading to more matches with CDK4/6 inhibitors (14% vs. 4%; p ≤ 0.001) or BRAF inhibitors (9% vs. 1%; p ≤ 0.001)." (PMID 37046628, 2023). "The IFN-I pathway plays a key antiviral role, suggesting that CDKN2A-deficient MPM might particularly benefit from oncolytic viral therapy, a novel anti-cancer strategy that exploits oncolytic viruses, which preferentially replicate in cancer but not in normal cells." (PMID 33072611, 2020).
cancer (continued). "Two other recurrently rearranged regions containing canonical cancer driver genes RB1 and CDKN2A were identified by this method but were not significant following multiple testing (FDR: q ≥ 0.2)." (PMID 30889380, 2019). "In another study they applied a marker panel (APC, CDKN2A/p16, and RASSF1) to detect cancer in 247 patients, and reported 53% sensitivity and, in cases without a previous history of cancer, >99% specificity." (PMID 18947422, 2008). "While the amplification of oncogenes (such as EGFR, c-ERBB2, c-MYC, and c-MET) is increasingly driving decision-making for precise cancer treatments, clinical applications of SCND of tumor suppressor genes, including CDKN2A, are still rare owing to the lack of a feasible detection assay." (PMID 36531022, 2022). "The majority of known driver gene amplifications (e.g., EGFR, ERBB2, MET, and MYC) and homozygous deletions (e.g., CDKN2A, PTEN, and RB1) were captured, with 320 RACSs (38%) containing at least one known putative cancer driver gene, in addition to 531 RACSs (62%) without known driver genes." (PMID 27397505, 2016). "Our findings indicate that methylation of CpG islands at the 5'end of the first exon of CDKN2A detected by MethyLight, but not by MSP, may serve as a specific marker of HCC since it was frequently found in HCCs and detected only in one non-cancer sample." (PMID 20569442, 2010). "We analyzed a group of genes that were upregulated in MSC lines compared to cancer cell lines, including transcription factors (ZBTB16, HAND2, and TWIST1), a cadherin regulating cell adhesion (CDH20), a receptor tyrosine kinase (PDGFR-α), and a negative cell cycle regulator (CDKN2A)." (PMID 39621192, 2025). "Some downregulated genes (EHF and MMP14), mainly involved in proliferation and cancer development, were not restored upon EZH2 inhibitor treatment, and some that were upregulated in KO samples retained or even increased their high expression after treatment (EFCAB6 and CDKN2A)." (PMID 38672463, 2024). "However, according to the 2020 International Cancer of the Pancreas Screening Consortium (CAPS), PDAC surveillance is recommended in CDKN2A carriers regardless of family history of PDAC, starting at age 40 or 10 years before than the youngest relative affected." (PMID 36980574, 2023). "While no studies have previously been published in other cancer cell lines for transient overexpression of TBX4 and 5, numerous studies have shown that transient overexpression of TBX2 or TBX3 does specifically affect senescence by targeting the tumor suppressor gene CDKN1A and B, and CDKN2A." (PMID 30425966, 2018). "Indeed, CDKN2A and TYMS showed strong positive staining in a subset, but not in all cancer samples." (PMID 21365010, 2011).
infection (106 papers, 2008 to 2025). The state of being infected such as from the introduction of a foreign agent such as serum, vaccine, antigenic substance or organism. "Once more, infection with the omicron variant resulted in a significant upregulation of CDKN2A in lung tissue when normalized to uninfected control tissue." (PMID 38095608, 2023). "VERO cells have a homozygous ≈9 Mb deletion on chromosome 12, causing the loss of CDKN2A/B genes, besides the type I interferon gene cluster (which probably explains why they are so infection-prone)." (PMID 33167404, 2020). "Because p16Ink4a was induced after lentiviral infection and more prominently after KrasG12D induction, two potent shRNA clones against Cdkn2a encoding p16Ink4a and p19Arf were added to the second infection, along with shPten and shLuc, to avoid cell cycle arrest." (PMID 34172714, 2021). "However, following infection, CDKN2A expression (a gene linked to cell senescence) declined, resulting in increasing telomerase activity that gradually restored the telomere length to pre-infection levels over 1 year." (PMID 39837488, 2025). "Among five samples which showed diffuse strong positive expression in p16 IHC, all had wild type form of CDKN2A, while three had RB1 frameshift insertion mutation and the other two had high-risk HPV (type 16) infection." (PMID 38902320, 2024). "In the DLD-1 cell line, the CDKN2A expression induced by the CMV promoter at four weeks after infection was still significantly higher than that induced by the hACTB promoter." (PMID 25170953, 2014). "Possible molecular targets of miRNA-4634 during infection may include genes such as cyclin-dependent kinase inhibitor 2A (CDKN2A) and Toll-like receptor 8 (TLR8)." (PMID 39795977, 2024). "Although transcript levels of Cdkn2a (which encodes p16) were not markedly enhanced during infection, its expression was higher in infected, aged hamsters relative to infected, young hamsters." (PMID 37414987, 2023). "Another possible explanation for accelerated telomere shortening and increased CDKN2A levels in peripheral blood could be a change in cell composition during infection." (PMID 34548530, 2021). "To ascertain whether p16INK4A plays a role in the observed DNA polymerase depletion, we used an shRNA approach to knockdown CDKN2A (p16 INK4A) expression after RasG12V infection." (PMID 33961649, 2021). "Similarly, infection of cultured renal cells from wild type mice with a lentiviral vector expressing both shRNA-Tsc2 and shRNA-Cdkn2a (shRNA-Tsc2 + Cdkn2a) increased proliferation rate compared with shRNA-Cdkn2a knockdown and allowed growth in soft agar." (PMID 29133867, 2017). "However, in the MCF-10A cell line, the difference in the level of induced CDKN2A expression found at two days after infection was diminished, and the CDKN2A expression induced by the hACTB promoter was marginally higher, at four weeks after infection." (PMID 25170953, 2014). "Patients with high CDKN2A expression showed higher immune scores of APC_co_differentiation, CD8+-T-cells, Check-point, HLA, Infection-promotion, MHC-class-I, NK-cells, T-cell_co_differentiation, Tfh, and Th1-cells compared to those with low CDKN2A expression." (PMID 41341386, 2025). "Cell cycle arrest was confirmed by the upregulation of p16 (CDKN2A), E2F1 and E2F8 after 24 h post infection with omicron." (PMID 38095608, 2023). "The conclusion is that MYCN mediated anti-inflammatory response, CDKN2A mediated ion-channel transport and ZBP1 mediated leishmania-infection." (PMID 37878133, 2023). "To determine the expression of cellular senescence-related mRNA, we analyzed CDKN2A, CDKN1A, MMP3, and Lamin B1 in the slices 8 d post infection." (PMID 37163429, 2023). "On the other hand, the expression levels of BCL2, CDKN2A, IL-6, and PPARA remained similar in both male and female mice after infection but were significantly upregulated in male mice after infection in combination with exogenous SP-A2 (1A0) protein." (PMID 35844510, 2022).